DIO3OS (DIO3 opposite strand upstream RNA)
Diseases named in the same sentence as DIO3OS in open-access papers (continued):
Sharing a sentence is not in itself a finding about the gene and the disease.
tumor (7 papers, 2016 to 2025). "We also verified that ALDOA was the direct target of miR-122, and the tumor suppressive effects caused by DIO3OS knockdown or miR-122 overexpression could be rescued by re-expression of ALDOA in PC cells." (PMID 31384177, 2019). "As far as the tumor nodule number and weight in the lungs were concerned, DIO3OS knockdown inhibited lung metastasis of SaoS-2 cells in vivo." (PMID 37752544, 2023). "Consistently, in the xenograft tumor model, ZEB1 knockdown significantly neutralized DIO3OS deficiency‐induced tumor growth." (PMID 37271897, 2023). "Depletion of DIO3OS significantly accelerated tumor growth in vivo and strongly increased the tumorigenesis frequency of Huh7 cells after subcutaneous injection of a series of cell dilutions." (PMID 37271897, 2023). "Consistent with the in vitro results, subcutaneous xenograft models showed that DIO3OS overexpression significantly retarded the growth rate and reduced the tumor weight of SK‐Hep1 cells." (PMID 37271897, 2023). "Our data support that miR-122 served as a novel tumor suppressor in PC by controlling the expression of DIO3OS." (PMID 31384177, 2019). "In addition, xenografts with DIO3OS upregulation exhibited more intensive Ki67 staining than those with control DIO3OS expression, supporting the pro-tumor role of DIO3OS in vivo." (PMID 36418319, 2022). "Through online predictive tools and functional experiments, we found that DIO3OS could bind directly to microRNA-122 (miR-122) and inhibited its expression, which functioned as a tumor suppressor in PC cells." (PMID 31384177, 2019). "The depletion of DIO3OS could suppress the tumor growth, and the overexpression of DIO3OS significantly increased tumor growth." (PMID 31384177, 2019). "In addition, overexpression of DIO3OS led to a significantly reduced xenograft incidence of SK‐Hep1 cells in the subcutaneous transplantation of serially decreasing numbers of tumor cells in nude mice, suggesting an in vivo repressing role of DIO3OS in HCC stemness." (PMID 37271897, 2023). "Thus, to explore the mechanism by which DIO3OS functions in PC, we searched for candidate miRNAs and confirmed that DIO3OS could compete with miR-122 and other miRNAs to tumor growth and invasion." (PMID 31384177, 2019). "To confirm that DIO3OS is downregulated in HCC, we profiled its expression in 34 pairs of clinical samples from HCC tumor tissues and matched adjacent non‐tumor tissues using real‐time RT‐PCR." (PMID 37271897, 2023). "lncRNAs such as DIO3OS, EMX2OS, KCNQ1DN, KCNQ1OT1, LOH12CR2, and RFPL1S have been shown to associate with a negative gene signature, which links lncRNA to tumor suppression mechanisms." (PMID 41300873, 2025). "DIO3OS and STARD13-AS were observed to be overexpressed in the tumor group." (PMID 37470034, 2023). "Furthermore, ectopic DIO3OS overexpression markedly inhibited the stemness of HCC cells, as determined by tumor sphere formation and ALDEFLUOR assays." (PMID 37271897, 2023). "Moreover, DIO3OS expression positively correlated with both tumor size (P = 0.0142) and Ki67 index (P = 0.0010), but not with lymph node or distant metastasis." (PMID 36418319, 2022). "Importantly, to further confirm the existence of the DIO3OS/miR-122/ALDOA axis in PC tissues, we detected the levels of miR-122 and ALDOA in PC samples and non-tumor samples obtained from the TCGA database using the MethHC database and UALCAN web server, respectively." (PMID 31384177, 2019).
DIO3OS also shares sentences with these, for which no sentence is quoted: non-small cell lung carcinoma (2 papers); pancreatic cancer (2); benign prostatic hyperplasia (1); colon cancer (1); diabetes mellitus (1); metabolic disease (1); myomatous neoplasm (1); nerve sheath tumors (1); papillary thyroid carcinoma (1); sarcoma (1); squamous cell lung carcinoma (1); thyrotoxicosis (1); ulcerative colitis (1).